KRAS (KRas proto-oncogene, GTPase)
Diseases named in the same sentence as KRAS in open-access papers (continued):
Sharing a sentence is not in itself a finding about the gene and the disease.
breast cancer (continued). "We aimed to evaluate whether the hormone receptor expression, HER2 and MYC genes and their protein status, and KRAS codon 12 mutations may be prognostic or predictive biomarkers of breast cancer." (PMID 23555992, 2013). "Furthermore, we aimed to investigate the association of the KRAS variant with breast tumor characteristics among Slovenian postmenopausal sporadic breast cancer cases stratified by hormone replacement therapy (HRT) use." (PMID 22436609, 2012). "Somatic KRAS mutations are found in pancreatic cancer (60% of tumors), colon cancer (32%), lung cancer (17%) and, with a much lower incidence (5%), in leukemias and breast cancer." (PMID 20385028, 2010). "Thus, the finding of heightened expression of HIF1α and HIF target genes in patients’ breast cancers with amplified KRAS can now be directly related to a perturbation of KRAS activity and likely that of more commonly mutated downstream elements in the KRAS pathway." (PMID 34294889, 2022). "Recently, KRAS mutations have been reported to be involved in human cancer, including nasopharyngeal carcinoma, ovarian cancer, lung cancer, pancreatic cancer, oral squamous cell carcinoma, esophageal squamous cell carcinoma, colorectal cancer, breast cancer and so on." (PMID 26392416, 2015). "In addition, we found that nucleic acids prepared from CTCs captured using the CellSearch® RUO Profile kit were also amenable to biomarker assays including a qRT-PCR gene expression assay for breast cancer molecular subtype, and a PCR-based assay for KRAS mutations." (PMID 20838621, 2010). "CONCLUSIONS: Sorafenib-HQ combination offers potent, context-specific synergy for KRAS-mutant breast cancer via Raf inhibition and autophagy blockade, enabling dose reductions and apoptosis enhancement." (PMID 41928324, 2026). "The review also covers emerging candidates like an miR-221 inhibitor and various strategies for breast cancer, such as targeting Bcl-2, KRAS, and specific miRNAs." (PMID 42076082, 2026). "In KRAS-transformed breast cancer cells, RRAS2 activates a subset of PI3Kα, promoting PI3K-dependent tumorigenesis." (PMID 39788953, 2025). "Intriguingly, we discovered that the promoter region of KRAS probably formed a novel G4 proximal to the TSS based on the occurrence of SNVs in breast cancer which is distinct from the well-established KRAS-G4 previously." (PMID 40725120, 2025). "Among the three isoforms of RAS (HRAS, NRAS, KRAS), aberrant KRAS signaling drives 30% of all human cancers and 5% of breast cancer." (PMID 40736275, 2025). "Strikingly, a new G4 motif is formed in the promoter region of KRAS which exhibits a markedly increased expression level in breast cancer." (PMID 40725120, 2025). "Although we are not clear about how this newly formed G4 induced by SNV correlates with the overexpression of KRAS, it will pave the way for drug innovation in treatment of KRAS-mutant breast cancer patients." (PMID 40725120, 2025). "The opposite effect of the PCAIs-induced inhibition of AKT phosphorylation in MDA-MB-231 cells, a KRAS-mutant breast cancer, is interesting." (PMID 38540084, 2024). "Activation of KRAS promotes the mesenchymal features of basal-type breast cancer Activation of KRAS promotes the mesenchymal features of basal-type breast cancer Exp." (PMID 39281650, 2024).
breast cancer (continued). "In the specific case of breast cancer, up to 23% of premenopausal women with TNBC have been shown to have higher rates of mutations in KRAS gene." (PMID 38571493, 2024). "This not only highlights the significance of KRAS in promoting therapy resistance but also underscores its role in driving the development of the most aggressive forms of breast cancer." (PMID 38571493, 2024). "Thus, while decreased KRas, beta-catenin, and TNFα signaling likely underly the attenuation of tumor growth by Hpa2-Nuc in pre-clinical models, activation of the immune system likely play a suppressive role in breast cancer patients in which nuclear localization of Hpa2 was retained." (PMID 38519456, 2024). "Since these growth-stimulating factors require KRAS for signaling, KRAS-targeting agents such as PCAIs have the potential to benefit a broad spectrum of breast cancer patients." (PMID 38540084, 2024). "While KRAS is mutated in only 4% of breast cancer cases, the MAPK pathway is activated in approximately 50% of breast cancers." (PMID 38003387, 2023). "Within the 7 breast cancer cases, two cases showed a BRCA2 nonsense variant (p.R2318* and p.K3326*), one case showed ERBB3 G234R, one case showed KRAS G12V, and one case showed ARID1A P453fs." (PMID 36125633, 2023). "This study suggests that the oncogenic KRAS-ERK/p38-EGR1-KLF4 signaling axis is a potential regulatory signaling pathway that mediates VM in aggressive breast cancer cells." (PMID 37762678, 2023). "In KRAS wild-type breast cancer cells, exposure to IR (4 Gy) induces YB-1 phosphorylation as early as 5 min post-IR." (PMID 36313934, 2023). "Ras dosage is known to be important for KRAS-mediated progression of pancreatic and breast cancer and KRAS and NRAS contributions to myeloid malignancies." (PMID 36864243, 2023). "Importantly, the same as in human tumors, the majority of KRAS mutations identified in canine tumors are located at mutational hotspot G12, including G12A (detected in 2 melanomas), G12V (in 2 mammary carcinomas), G12D (in 1 mammary carcinoma and 1 squamous cell carcinoma), and G12C (in 1 melanoma)." (PMID 37414794, 2023). "Nevertheless, breast cancer with high immune activity not only enriched immune-related gene sets, but also enriched pro-cancer gene sets: KRAS signaling, PI3K/AKT/MTOR signaling, and apical surface gene sets." (PMID 35945417, 2022). "We found that KRASG12C was clonal (clonality > 0.9) in cancer types except for patients with CRC and breast cancer, in which clonality was bimodal, suggesting that KRAS is a more common resistance mechanism in these tumor types." (PMID 35862868, 2022). "In the dose-expansion phase, patients with CDK4/6i-treated breast cancer, or KRAS-mutant (KRASmut) non-small-cell lung cancer (NSCLC) received the MTD." (PMID 36291780, 2022). "Allegrezza et al28 have shown that trametinib reduces MDSC myelopoiesis and exhibits enhanced efficacy against KRAS-driven breast cancer due to the activation of CD8+ T cells." (PMID 35292516, 2022). "High expression of KRAS is associated with poor prognosis in blood cancer (GSE2658, HR = 0.55, Cox p-value = 0.00147), breast cancer (GSE11121, HR = 1.45, Cox p-value = 0.000745." (PMID 35563733, 2022). "We have recently shown that heteronemin suppressed ERK1/2 activation in breast cancer cells, similar to this study in HT-29 cells (KRAS WT CRC)." (PMID 36005485, 2022).
breast cancer (continued). "While canonical mutations in Ras/MAPK genes (for example KRAS G12V and BRAF V600E) are rare in breast cancer, Ras/MAPK is often overactivated in response to pathway deregulation." (PMID 35850776, 2022). "In summary, the prepared arene Ru(II) complexes can be developed as a promising candidate for targeting G-quadruplex structure to induce the apoptosis of breast cancer cells via binding and stabilizing KRAS G-quadruplex conformation on oncogene promoter." (PMID 35630522, 2022). "The inhibition of ICMT was shown to lead to a decrease in self-renewal/stem potential in KRAS-driven breast cancer cells." (PMID 36430403, 2022). "It has been reported that some tRNA fragments, such as ts-47s and ts-46s, are upregulated by KRAS and PIK3CA mutations, respectively, leading to breast cancer chemoresistance." (PMID 34489556, 2022). "Of note, only the MDA-MB-231 breast cancer cell line showed a dependency on KRAS, CALM3 as well as PPP2CA." (PMID 35617282, 2022). "Collectively, treatment with S6 inhibited STAT3 phosphorylation and attenuated the downstream TGF-β/KRAS signaling pathways, which in turn inhibited breast cancer progression." (PMID 36581888, 2022). "Gynecologic cancers are known to harbor low rates of actionable mutations, especially in comparison to lung, colon, and breast cancers which frequently express alterations in EGFR, KRAS, and HER2, respectively." (PMID 35267660, 2022). "KRAS was reported to participate in the tumorigenesis and progression of breast cancers, and it plays a central role in the activation of many pathways, such as AKT/MEK/ERK signaling." (PMID 34696797, 2021). "The immunoblot analysis of the 6 mammary tumors that express oncogenic KRAS from its endogenous locus showed that the basal-like cancers (tumors 4 to 6) express EpCAM, E-cadherin, and CK14 but lack expression of N-cadherin and CK8." (PMID 34145248, 2021). "The persistent activation of mutant KRAS under the control of the MMTV-tTA in the mammary gland was sufficient to initiate the development of palpable mammary tumors after an average latency of 160 ± 41 days (right)." (PMID 34145248, 2021). "Gene-set enrichment analysis (GSEA) uncovered a significant association within the hPRLrIhi/hPRLrLlo cohort with basal-like breast cancer, metastasis, and oncogenic KRAS actions." (PMID 33772010, 2021). "In breast cancer progression, miRNA-30 c also play a role by inhibiting KRAS signaling, histone deacetylase 9 (HDAC9), or coactosin-like protein 1 (COTL1)." (PMID 34503377, 2021). "Multiple oncogenic pathways, such as mTORC1 signaling, E2F targets, KRAS signaling, and the estrogen response have been found up-regulated in breast cancer cells with acquired resistance to CYH3329." (PMID 33446653, 2021). "To demonstrate the applicability of the new MMTV-Flp strain to model breast cancer, we used this transgene for the recombinase-induced activation of an oncogenic mutant of KRAS that is expressed from its endogenous locus." (PMID 34675248, 2021). "In concordance with the observed dissimilarities in their histopathological appearance, mammary tumors that express oncogenic KRAS under the control of the EF1-tTA exhibited gene expression profiles that were different from luminal-type cancers." (PMID 34145248, 2021).
breast cancer (continued). "For instance, while KRAS mutation is very frequent in CRC (about 40% of the cases), it is much less frequent in breast cancer and, in particular, in ER positive breast cancers (less than 1%), the tumor subtype in which CDK4/6i are more active." (PMID 34654798, 2021). "Initially, mammary tumors expressing oncogenic KRAS were comprised of pockets of cancer cells that were E-cadherin or N-cadherin positive (middle)." (PMID 34145248, 2021). "We generated a third cancer model to confirm that an inducible gain-of-function of endogenous KRAS in the mammary epithelium also results in the development of basal-like and claudin-low mammary cancers." (PMID 34145248, 2021). "Among the two patients with breast cancer who achieved SD, one harbored an Akt1E17K mutation with a CDH1 frameshift deletion and another harbored a PIK3CA H1047R mutation with a KRAS missense mutation." (PMID 33723724, 2021). "In a proof-of-principle experiment, we used the dual recombinase approach in this study to conditionally delete JAK1 in KRAS-transformed mammary cancer cells." (PMID 34675248, 2021). "MDA-MB-231 display mutations in both KRAS and BRAF, the work summarized below utilizes a combination of MDA-MB-231 and transformed MCF-10A cells to dissect the contributions of autophagy to breast cancer pathogenesis." (PMID 34503118, 2021). "In a proof-of-principle experiment, we conditionally deleted the JAK1 tyrosine kinase in KRAS-transformed mammary cancer cells using the dual recombinase approach and found that lack of JAK1 was sufficient to block the constitutive activation of STAT3." (PMID 34675248, 2021). "Here we show that the forced expression of active YAP in MDA-MB-231 cells (a highly aggressive human breast cancer cell line that carries a mutant KRAS gene) also promoted their metastatic ability in transplanted immunodeficient mice." (PMID 31772328, 2020). "We found that miR-143 functions as a tumor-suppressor miR in breast cancer by targeting the KRAS signaling pathway and enhancing anti-tumoral immunity." (PMID 32370060, 2020). "We found that suppression of ICMT results in reduced self-renewal/stemness in KRAS-driven pancreatic and breast cancer cells." (PMID 32561852, 2020). "KRas activation is involved also in the induction of aggressive ER+ mammary tumors in the NRL-PRC murine model, defined by mammary-selective transgenic rat prolactin ligand rPrl expression." (PMID 32210163, 2020). "The expression of mutant KRAS led to a multifocal onset of mammary tumors that co-expressed the nuclear GFP reporter." (PMID 31937792, 2020). "With this GSVA-based scoring system, we have shown the clinical relevance, such as prognosis and treatment response, for the KRAS, G2M checkpoint, and E2F pathways in breast cancer." (PMID 32933189, 2020). "In conclusion, miR-143 appears to have a role in the suppression of breast cancer via the targeting of KRAS and its effector molecules." (PMID 32370060, 2020). "Ras/MAPK signaling can be activated by a variety of mechanisms, including activating mutations in KRAS, NRAS, HRAS, or BRAF, which are commonly mutated in cancers but are rarely observed in primary breast cancers." (PMID 32634121, 2020). "Leading-edge analysis (for genes that contributed most to enrichment in pathways) showed genes that are upregulated downstream of KRAS in lung or breast cancer (e.g., CXCL3, ADAM8, and L.I.F.)." (PMID 32455851, 2020).
breast cancer (continued). "In a previous study, we demonstrated for the first time that exposure to a clinically relevant dose of ionizing radiation (IR) induces YB-1 phosphorylation at S102 in KRAS wild-type breast cancer cells, detected up to 30 min after irradiation." (PMID 33003386, 2020). "While these studies bring to light a potentially important role for KRAS signaling in breast cancer initiation, the work presented herein describes the first instance of Kras mutagenesis as a spontaneous driver of mammary tumor metastasis." (PMID 32463822, 2020). "Meanwhile, basal expression of KRAS mRNA was checked in a pancreatic and breast cancer cell panel according to the data from cancer cell line Encyclopedia (CCLE)." (PMID 30654191, 2019). "For example, oncogenic PI3K and KRAS mediated-mTORC1 activation promote nuclear accumulation of mature SREBP1 in breast cancer cell." (PMID 31772672, 2019). "The enrichment of KRAS signaling can be explained by published evidence supporting KRAS activation in basal-type breast cancer cells compared to luminal cells." (PMID 31729402, 2019). "The data gathered so far demonstrate that MG dicarbonyl stress induces (hyper)activation of MEK/ERK signalization, independently of KRAS status, which sustains the regulation of pro-metastatic gene expression and migratory capacity of breast cancer cells." (PMID 30674353, 2019). "Only KRAS G13D ectopically expressed in MCF10A breast cancer cells promoted an increase in total and phosphorylated EGFR." (PMID 31681616, 2019). "We, therefore, used confluent MCF-7 breast cancer cells to visualize and quantify KRAS and PtdSer mislocalization." (PMID 31451509, 2019). "Meanwhile, malignant basal-type (MDA-MB231, MDA-MB-436, and BT20) breast cancer cells had a higher expression level of KRAS compared with luminal-type breast cancer cell lines (MCF7, SKBR3, and T47D)." (PMID 30654191, 2019). "Since IR-induces YB-1 phosphorylation in KRASwt breast cancer cells, including MCF7 cells, it is expected that irradiation and other YB-1 stimuli, such as growth factors and KRAS mutation, will induce YB-1 nuclear translocation." (PMID 30126195, 2018). "Here the authors show cetuximab-guided Avidin-Nucleic-Acid-Nanoassemblies to be superior to cetuximab-doxorubicin conjugate, and show its efficacy in KRAS mutant breast cancer, allowing for therapeutic expansion of anti-EGFR therapy." (PMID 30287819, 2018). "Somatic mutations in KRAS are common in gastric cancer tumors, NRAS is frequently mutated in melanoma, and HRAS to some extent in breast cancer." (PMID 30597917, 2018). "The authors added that the adoption of this technology in hospitals has already improved the manner in which healthcare practitioners detect and monitor KRAS, BRAF, and EGFR mutations in patients with lung, colon, and breast cancer, respectively." (PMID 29728089, 2018). "Analysis of reverse-phase protein array (RPPA) data of human basal-like breast cancer samples from The Cancer Genome Atlas revealed that BCL-XL expression was correlated with KRAS and with phosphorylation levels of c-RAF at S338 that mark RAS activation." (PMID 29066722, 2017). "In contrast, entities such as breast cancer or HNC display a predominance of PIK3CA mutations (around 40%, for an overall mutation rate of KRAS, NRAS and HRAS inferior to 5% in both cases)." (PMID 28532501, 2017). "Altogether, these clinical results are consistent with mutual influences between BCL-XL and KRAS activity in human breast cancers." (PMID 29066722, 2017).